SNORD48 (small nucleolar RNA, C/D box 48)
Synonyms: U48; RNU48
Gene: Small nucleolar RNA gene on chromosome 6 (31,835,263 to 31,835,326, forward strand). Ensembl gene ENSG00000201823.
Gene Ontology:
Biological process: RNA processing
Cellular component: nucleolus
Homologues: Orthologues: chimpanzee SNORD48 (97% identical), macaque SNORD48 (95% identical), pig SNORD48 (86% identical), mouse Gm25744 (83% identical), rat Snord48 (83% identical).
Diseases named in the same sentence as SNORD48 in open-access papers:
SNORD48 is named in the same sentence as 4 diseases in open-access papers, as found by Europe PMC text mining. Sharing a sentence is not in itself a finding about the gene and the disease. The quoted sentences say what the papers report.
endometrial cancer (1 paper, 2024). Primary or metastatic malignant neoplasm involving the endometrium (mucous membrane that lines the endometrial cavity). "Our study suggests that upregulation of miR-205-5p and downregulation of miR-222-3p and SNORD48 may influence development of endometrial cancer." (PMID 38542261, 2024).
cancer (4 papers, 2011 to 2018). A tumor composed of atypical neoplastic, often pleomorphic cells that invade other tissues. "To validate the microarray results by reverse transcription quantitative PCR (RT-qPCR) and to identify an appropriate endogenous reference, we primarily assayed the expression of SNORD44 (RNU44), SNORD48 (RNU48), U6snRNA and miR-26b in 10 cancer and 2 control samples." (PMID 27056547, 2016).
SNORD48 also shares sentences with these, for which no sentence is quoted: head and neck cancer (1 paper); renal cell adenocarcinoma (1).